LYPLA2P1 (LYPLA2 pseudogene 1)
Synonyms: dJ570F3.6; APT; formerly LYPLA2L
Gene: Processed pseudogene on chromosome 6 (33,365,548 to 33,366,243, reverse strand). Ensembl gene ENSG00000228285.
Diseases named in the same sentence as LYPLA2P1 in open-access papers:
LYPLA2P1 is named in the same sentence as 14 diseases in open-access papers, as found by Europe PMC text mining. Sharing a sentence is not in itself a finding about the gene and the disease.
LYPLA2P1 shares sentences with these, for which no sentence is quoted: thrombosis (9 papers); Arterial thrombosis (3); antiphospholipid syndrome (1); COVID-19 (1); endothelial dysfunction (1); hypercoagulability (1); influenza (1); mononeuropathy (1); pancreatitis (1); parathyroid tumors (1); systemic lupus erythematosus (1); Thrombocytopenia (1); thrombophilia (1); venous thromboembolism (1).